CRP (C-reactive protein)
Diseases named in the same sentence as CRP in open-access papers (continued):
Sharing a sentence is not in itself a finding about the gene and the disease.
cardiovascular disease (continued). "In the decade that have followed the initial investigation ofCRP in cardiovascular disease, dozens of studies have accumulated evidence thatstrongly associates inflammation as measured by CRP with a number of outcomesassociated with a range of cardiovascular outcomes." (PMID 39077721, 2022). "CRP has been widely proposed as a risk factor and an indicator of cardiovascular disease." (PMID 36645038, 2022). "It is well established that CRP concentrations increase in response to tissue injury or inflammation and hs-CRP has been endorsed by multiple guidelines as a biomarker of atherosclerotic/cardiovascular disease risk." (PMID 35268057, 2022). "Assessment of risk of cardiovascular disease based on serum Hs-CRP level." (PMID 36381804, 2022). "CRP is a risk factor for several disease, including cardiovascular disorders." (PMID 35243104, 2022). "Today, CRP is a well-established biomarker associated with inflammation in cardiovascular disease." (PMID 35203485, 2022). "According to the American Heart Association, elevated serum hs-CRP level is well-established as a prognostic marker of cardiovascular disease with a cut-off value of 3 mg/L that can detect patients at high risk, while a level of 1–3 mg/L is associated with a moderate risk." (PMID 33800490, 2021). "Numerous studies confirmed that CRP was associated with cardiovascular disease." (PMID 33564690, 2021). "Furthermore, these patterns explain how CRP can predict the risk of cardiovascular diseases even in individuals with normal lipid levels." (PMID 33498799, 2021). "Thus, the Monitoring of Trends and Determinants in Cardiovascular Disease (MONICA) study demonstrated that elevated levels of CRP were associated with an increased risk of coronary events in healthy middle-aged men." (PMID 33803115, 2021). "Also, high sensitivity CRP > 1 mg/L is known to be associated with a mild risk of cardiovascular disease, while levels 1-3 mg/L represent moderate risk and > 3 mg/L, high risk." (PMID 34868746, 2021). "The novel role of C-reactive protein in cardiovascular disease: risk marker or pathogen." (PMID 34320066, 2021). "Additionally, the study also showed that patients with unstable AAA displayed higher CRP levels, a blood biomarker usually associated with the progression of cardiovascular disease." (PMID 35096635, 2021). "Unknown medical conditions, such as e.g. cardiovascular disease, may have caused some participants to avoid shift work, while exhibiting elevated CRP and pain symptoms." (PMID 33550437, 2021). "CRP, the representative acute phase protein, is sensitive for inflammation and tissue damage, and its elevated plasma level is correlated with increased risk of cardiovascular diseases." (PMID 34775377, 2021). "The promising findings on green tea and CRP suggested that green tea might reduce the risk of cardiovascular disease by lowering CRP concentrations in T2D patients." (PMID 33709113, 2021). "CRP is used as a marker for inflammation, typically used to predict cardiovascular disease risk." (PMID 34604282, 2021). "High-sensitivity C-reactive protein (hs-CRP), as an inflammatory mediator, may be useful for the prediction of the risk of cardiovascular disease (CVD) and assessment of nocturnal continuous positive airway pressure (nCPAP) therapy effect in OSAHS patients." (PMID 33204538, 2020). "As cardiovascular disease appears to be an inflammatory process leading to endothelial damage, several factors are additionally regarded to describe cardiovascular risk, including proinflammatory cytokines and C-reactive protein (CRP)." (PMID 32308675, 2020). "Our findings on the gender difference in the association of IMT and serum hs-CRP level with two SNPs of CRP gene suggested that hormones may play an etiologic role on IMT-related cardiovascular disease." (PMID 32214403, 2020). "CRP is a biomarker of inflammation which may constitute an independent risk factor for cardiovascular disease." (PMID 32957486, 2020).
cardiovascular disease (continued). "This study aimed to investigate the linkage between adipocytokines and insulin with the cardiovascular disease risk, with particular reference to the adipokines galectin-3, plasminogen activator inhibitor-1, and interleukin-1-beta, C-reactive protein, and monocyte chemoattractant protein." (PMID 32290863, 2020). "Therefore, it seems contradictory that E4, which is associated with low CRP, is a predictor of cardiovascular disease and mortality, and reduced longevity." (PMID 32646381, 2020). "Furthermore, there is recent development in isoforms of CRP, such as pentameric and monomeric isoforms, linked to cardiovascular diseases and inflammatory conditions, which need to be considered in future studies." (PMID 32397288, 2020). "CRP is a 115 kDa serum protein with a hydrated volume of 197.3 mm3, and is one of the most frequently used cardiac biomarkers with high specificity to diagnose and monitor cardiovascular diseases (CVDs), which are the leading cause of death worldwide." (PMID 33374119, 2020). "The detection of CRP levels may enable us to determine whether OSAS is associated with cardiovascular diseases, and CPAP treatment significantly reduces CRP levels, possibly further reducing the incidence of cardiovascular disease." (PMID 33214634, 2020). "Given clinical studies have showed that statins would confer less risk reduction of cardiovascular diseases in individuals with high serum C-reactive protein (CRP) levels, anti-inflammatory treatment is emerging as a complement to lipid-lowering treatment in ASCVD patients." (PMID 32885808, 2020). "Whether the CRP-mediated inflammatory response is involved in the damage associated with a high-salt diet in cardiovascular disease remains to be further explored and confirmed." (PMID 33250683, 2020). "The detected shifts in the amplitude of insertion loss in SAW sensors for different CRP concentrations may be useful in the diagnosis of risk of cardiovascular diseases." (PMID 33228249, 2020). "PAH exposure has been reported to be associated with increased CRP levels in humans; and it has been hypothesised that particle exposure may cause cardiovascular disease through particle-mediated acute phase response and lung inflammation." (PMID 31477116, 2019). "In addition, these pro-inflammatory cytokines are implicated in increased cardiac tissue CRP which is strongly associated with the onset of cardiovascular diseases." (PMID 30669379, 2019). "In a 2012 cross-sectional substudy of the Adventist Health Study-2, Blacks generally had higher levels of C-reactive protein (an inflammatory biomarker associated with cardiovascular disease) than Whites; however, vegetarian diets were associated with lower CRP levels." (PMID 31810250, 2019). "In addition, some studies have shown higher CRP levels in haemodialyzed malnourished patients vs. NN subjects, which is a risk factor for cardiovascular diseases." (PMID 31878925, 2019). "The association of C‐reactive protein (CRP) and serum 25‐hydroxyvitamin D [25(OH)D] and cardiovascular disease (CVD) remains unknown." (PMID 31020672, 2019). "In the future, follow-up studies would be of high interest to investigate if those BD patients of our sample with CRP risk variants and/or elevated CRP might be at an increased risk for cardiovascular disease." (PMID 31788733, 2019). "We suggest that an increase in miR-124 level induced by CRP might be associated with bad prognosis of cardiovascular diseases." (PMID 31063484, 2019). "Several polymorphisms in the CRP gene have been shown to be associated with changes in the serum protein concentration, such as the CRP -717T>C polymorphism, which appears to influence the serum protein concentration and the development of cardiovascular diseases." (PMID 30804931, 2019). "Consequently, the American Heart Association and CDC recommended guidelines for the incorporation of CRP into its cardiovascular disease risk stratification." (PMID 30813467, 2019).
cardiovascular disease (continued). "It is considered a non-specific marker of inflammation and the mechanism by which CRP contributes to cardiovascular disease risk is unknown." (PMID 31553765, 2019). "Being CRP concentration canonically linked to cardiovascular diseases and, consequently, to all-cause mortality, we also assessed the relationship between this marker of inflammation and both nutritional status and iron status on the one hand, and the quality of haemodialysis on the other." (PMID 31137583, 2019). "Indeed, its level in the plasma of patients with cardiovascular disease is useful as a biomarker of cardiovascular disease risk, at least as useful as C-reactive protein." (PMID 31231209, 2019). "Consistent with other studies, there are 19 SNPs within a 43 Kb span on chr 12 encompassing the HNF1A gene, a hepatic transcription factor which has been repeatedly found to affect CRP expression, as well as C12orf43, variants of which have been linked to cardiovascular disease and CRP expression." (PMID 31622379, 2019). "Salivary CRP also may be predictive of cardiovascular disease risk and appears to reliably discriminate between high and low levels of plasma CRP, using a clinically relevant cutoff of 3 mg/L." (PMID 31046830, 2019). "the serum myocardial enzymes and CRP levels proved that RA treatment may play a positive role in protecting the risk of serious cardiovascular diseases." (PMID 31887996, 2019). "For instance, peptides from CRP were strongly associated with the risk of death in our participants, recapitulating many previous reports, and biomarkers of inflammation have consistently been reported for cardiovascular disease and mortality." (PMID 29399943, 2018). "In 2011, Samaropoulos and coworkers demonstrated how an intensive glycemic control in middle- to old-aged type 2 diabetic patients, who already had or are at risk for cardiovascular disease, was associated with a reduction in high-sensitivity C-reactive protein (hs-CRP)." (PMID 30402502, 2018). "Appropriately large scale observational epidemiology firmly established that baseline CRP values are actually only a very modest risk marker for cardiovascular disease and Mendelian randomization studies proved that CRP itself is definitely not a causative risk factor." (PMID 30459761, 2018). "Dietary patterns may influence the risk of diseases through the effects of CRP, a marker of subclinical inflammation and predictor of cardiovascular disease." (PMID 29558396, 2018). "While prior studies in SSA have found elevated CRP, IL-6, and other markers of systemic inflammation which were associated with increased mortality and cardiovascular disease, there is a clear need for data on the relationship of inflammation with metabolic comorbidities." (PMID 30009182, 2018). "Long-term smoking has been known to lead to anti-oxidant imbalance and inflammation with elevated concentrations of C-reactive protein (CRP), both of which may cause cardiovascular disease." (PMID 28989978, 2017). "It was found that C-reactive protein (CRP) is significantly associated with cardiovascular disease." (PMID 29225964, 2017). "Hence, the aim of the present study was to evaluate cardiovascular disease (CVD) risk factors along with C-reactive protein levels measured by high-sensitive method (hsCRP) in a group of healthy males of university students (n = 101, 18–25 years old)." (PMID 28487812, 2017). "Surprisingly, there have been very few studies to compare ELISA with MS-based methods or to examine whether any post-translational modifications (PTMs) to CRP such as acetylation are associated with cardiovascular disease." (PMID 27713681, 2016). "In the present trial, approximately two-thirds of the children and adolescents had a higher intima-media thickness, elevated blood pressure levels and/or higher concentrations of lipids and CRP; all together, these are risk indicators for metabolic and cardiovascular disorders." (PMID 27417593, 2016).
cardiovascular disease (continued). "Although elevated CRP level of Africans is viewed as a beneficial factor of protection against infectious diseases, it could indicate increased risk to cardiovascular disease as well as other inflammation-dependent health conditions." (PMID 27298824, 2016). "The hypothesized effect of vitamin D on C-reactive protein (CRP) has received substantial attention as a potential means to alleviate the risk for cardiovascular disease." (PMID 27827910, 2016). "In addition to cardiovascular disease, CRP has been shown to be associated with a range of other morbidities including diabetes and cancer, and has also been shown to predict all-cause mortality." (PMID 27386859, 2016). "Elevated blood pressure and in particular the pulse pressure has been associated with an increased risk of cardiovascular disease and the underlying mechanism may be inflammation as demonstrated by elevated CRP levels." (PMID 27275343, 2016). "C-reactive protein (CRP) is a novel risk factor for cardiovascular disease (CVD)." (PMID 27827910, 2016). "However, little is known about CRP in young, healthy women and the risk for developing cardiovascular disease." (PMID 25861161, 2015). "The association of CRP with cardiovascular disease is often related to inflammation." (PMID 26576922, 2015). "The effect of Ox-LDL and CRP on the risk of cardiovascular disease has been reported." (PMID 25864817, 2015). "Indeed, high sensitivity C-reactive protein has been recommended for use in the risk stratification of cardiovascular disease in certain patient groups." (PMID 25730322, 2015). "However, relationship among changes in C-reactive protein and cardiovascular disease risk factors with lifestyle interventions can predict the disease." (PMID 25949827, 2015). "Evidence from Mendelian randomization has been used to prioritize investigation of certain biomarkers as causal risk factors for cardiovascular disease: for example lipoprotein(a), and interleukin-6 receptor; and to de-prioritize others: fibrinogen, C-reactive protein (CRP), and uric acid." (PMID 25773750, 2015). "In cardiovascular disease, R might be a function of C-reactive protein, a cardiovascular risk factor, and Z might be acute infection, which strongly raises C-reactive protein." (PMID 25530064, 2015). "The mechanism(s) through which physical activity positively influences specific inflammatory activity (e.g., CRP) associated with cardiovascular disease remains unclear." (PMID 26106588, 2015). "Specific CRP inhibition followed by use of CRP inhibitors in controlled clinical trials may be the only way to prove or disprove a causative role for CRP in cardiovascular disease." (PMID 24799767, 2014). "The CRP level is consistently associated with the risk of cardiovascular disease." (PMID 24782595, 2014). "The difference in the study population (e.g., primary vs. secondary prevention) may pertain to this discrepancy, although other risk factors including CRP have similar associations with cardiovascular disease in primary and secondary prevention." (PMID 24705587, 2014). "The elevation of CRP in RA could contribute to elevated traditional risk factors and increased susceptibility to cardiovascular disease in RA." (PMID 25337037, 2014). "For example, although five of the variants included in the present study, rs2293791, rs7310409, rs2464196, rs2259816, and rs1169310, have been recently linked with changes in CRP, a marker for cardiovascular disease, their direct involvement in CAD manifestation remains disputable." (PMID 25057215, 2014). "If treatment of at-risk patients with a CRP lowering drug is found to lower the risk, then that would certainly settle the ongoing debate about whether CRP plays a role in cardiovascular disease." (PMID 24803739, 2014). "As our patients were already compliant with CPAP therapy, any further reduction in CRP could reflect further decrement in cardiovascular disease risk and progression." (PMID 25136550, 2014).
cardiovascular disease (continued). "Prior studies also found that IL-6, TNF-α, and CRP are associated with cardiovascular diseases." (PMID 27429271, 2014). "Vitamin C supplementation with its CRP-lowering effect could be a simple and useful method in modifying inflammation status, and a potential goal for reducing cardiovascular disease risk in patients on hemodialysis." (PMID 24719806, 2014). "However, it is important to emphasize that these values are above the value (>3.0 mg/L) used to determine groups at high risk of cardiovascular disease, which is based on CRP." (PMID 25045665, 2014). "In addition, serum CRP, an independent risk factor for cardiovascular diseases, has been found to be associated with HDL-C in the population." (PMID 24587064, 2014). "Moreover, increased levels of CRP are recognized as an independent risk factor of future cardiovascular events among healthy subjects, as well as in patients with known cardiovascular disease." (PMID 25538852, 2014). "Though impact of ST products on various risk factors for cardiovascular disease such as C reactive protein, total cholesterol, HDL-cholesterol, LDL-cholesterol, triglycerides, fibrinogen etc. was discussed in this paper, it did not touch upon the relationship of ST and homocysteine." (PMID 24376761, 2013). "CRP is the primary outcome in the study because it is a common surrogate of systemic inflammation and the only inflammatory outcome for which clinical recommendations exist (for patients at intermediate cardiovascular disease risk)." (PMID 24155956, 2013). "The underlying and combined mechanisms relating NT-proBNP to CRP and suPAR in cardiovascular disease are not well understood and we can therefore only speculate to explain our findings." (PMID 23516493, 2013). "Although a statistically significant association between the CRP level and cardiovascular disease has been observed in various studies, the relative contributions of CRP as a marker, causative agent, or consequence of the MIA syndrome are unclear in the dialysis population." (PMID 24007461, 2013). "The association of omega 3 intake with HCY and CRP for AA in the present study may be due, in part, to their susceptibility to cardiovascular disease; however, prospective studies are needed to make any determinations." (PMID 31667003, 2013). "Systemic inflammation may be measured with a variety of markers, including C-reactive protein (CRP), an acute-phase response protein implicated in a broad range of cardiovascular diseases." (PMID 23964267, 2013). "In addition, the acute-phase marker C-reactive protein (CRP) is strongly associated with cardiovascular disease, and can be used as a diagnostic or prognostic factor." (PMID 24385966, 2013). "Also, the use of statins in patients with cardiovascular disease was associated with both a lowered C-reactive protein and a reduced frequency of circulating of CD4+CD28null T cells." (PMID 24288592, 2013). "The lack of difference in CRP levels in that study could be explained by the fact that elevated CRP levels have been identified as an independent risk factor for cardiovascular disease and implicated in cardiovascular outcomes." (PMID 24222882, 2013). "CRP and fetuin-A are both markers for inflammation and cardiovascular disease that could be associated with patency loss." (PMID 23557085, 2013). "In recent years, CRP has emerged as a possible potent risk marker for cardiovascular diseases." (PMID 22834778, 2012). "Additionally, the mean CRP value of our sample (2.72 mg/L) falls just below the high-risk category for cardiovascular disease events according to the American Heart Association." (PMID 22461977, 2012). "Conversely, Caroline and collegues found that CRP levels are not independently associated with first cardiovascular events in older individuals, and increasing age seems to attenuate the association between plasma CRP levels and the risk of cardiovascular disease." (PMID 22834778, 2012).